PPA2 (inorganic pyrophosphatase 2)
Description:
Hydrolyzes inorganic pyrophosphate. This activity is essential for correct regulation of mitochondrial membrane potential, and mitochondrial organization and function.
Synonyms: HSPC124; FLJ20459; SCFAI; SCFI; SID6-306
Tractability: PROTAC: ubiquitination databases record sites on it; its protein half-life has been measured.
Gene: Protein-coding gene on chromosome 4 (105,369,077 to 105,474,113, reverse strand). Ensembl gene ENSG00000138777.
Subcellular location: Mitochondrion
Subcellular location (Human Protein Atlas): Mitochondria
Pathways (Reactome):
Metabolism: Pyrophosphate hydrolysis
Metabolism of proteins: Mitochondrial tRNA aminoacylation
Gene Ontology:
Molecular function: inorganic diphosphate phosphatase activity; magnesium ion binding; protein serine/threonine phosphatase activity
Biological process: diphosphate metabolic process; regulation of mitochondrial membrane potential; phosphate-containing compound metabolic process
Cellular component: mitochondrion; mitochondrial matrix; cytoplasm; synapse
Genetic constraint (gnomAD): Loss-of-function variants: 27 observed, 28.12 expected, observed/expected ratio (o/e) 0.96, 90% interval 0.71 to 1.32. The upper end of that interval is the gene's LOEUF score, 1.32, which puts it in group 5 of 6, group 1 being the genes least tolerant of losing a copy. Missense variants: 325 observed, 304.76 expected, observed/expected ratio (o/e) 1.07, 90% interval 0.97 to 1.17. Synonymous variants: 107 observed, 110.58 expected, observed/expected ratio (o/e) 0.97, 90% interval 0.83 to 1.14.
Gene-disease validity (ClinGen):
ClinGen rates the evidence that PPA2 causes each of these diseases.
dilated cardiomyopathy (autosomal recessive): Strong. Cardiomyopathy which is characterized by dilation and contractile dysfunction of the left and right ventricles.
Homologues: Orthologues: chimpanzee PPA2 (100% identical), macaque PPA2 (97% identical), pig PPA2 (84% identical), rabbit PPA2 (84% identical), dog PPA2 (83% identical), mouse Ppa2 (76% identical), rat Ppa2 (74% identical), tropical clawed frog ppa1 (60% identical), guinea pig PPA2 (58% identical), zebrafish ppa2 (57% identical), Drosophila melanogaster Nurf-38 (49% identical), Caenorhabditis elegans pyp-1 (46% identical). Paralogues in human: PPA1 (54% identical).
Diseases named in the same sentence as PPA2 in open-access papers:
PPA2 is named in the same sentence as 42 diseases in open-access papers, as found by Europe PMC text mining. Sharing a sentence is not in itself a finding about the gene and the disease. The quoted sentences say what the papers report.
cardiomyopathy (5 papers, 2016 to 2025). A disease of the heart muscle or myocardium proper. "PPA2 encodes a mitochondrially located inorganic pyrophosphatase implicated in progressive and lethal cardiomyopathies." (PMID 31705601, 2020). "We identified two sisters with biallelic variants in PPA2, which encodes a mitochondrially located inorganic pyrophosphatase (PPase) that is implicated in progressive and lethal cardiomyopathies." (PMID 31705601, 2020). "Moreover, a large Finnish cardiomyopathy registry of severe childhood cardiomyopathy (KidCMP) recently included two cases (index case + brother, out of 66) with a PPA2 biallelic variant who died at 8 and 5 months of age, respectively." (PMID 31705601, 2020). "Given that the incidence of “severe” childhood cardiomyopathy is ~0.50 per 100,000 population under the age of 10–15 years, the estimated the incidence of cardiomyopathy due to PPA2 biallelic variants would be approximately 0.01 per 100,000 (1 per 10,000,000) pediatric population." (PMID 31705601, 2020). "It was stated that myocardial fibrosis was a consistent finding and might help to discriminate PPA2-related cardiomyopathy from viral myocarditis." (PMID 37269378, 2023). "In cases of severe PPA2 dysfunction, ATP depletion has an acute effect and lactic acidosis and cardiomyopathy occurs prior to chronic damage developing, which could lead to acute symptoms in the presence of secondary triggers." (PMID 27523597, 2016). "Thus, fibrosis may help discriminate between PPA2-related cardiomyopathy and viral myocarditis when individuals present with acute heart failure." (PMID 34400813, 2021). "Despite what we know of the biology of PPA2, admittedly we do not have a true understanding of how the cellular deficits lead to organ‐level dysfunctions that most likely leads to death, cardiomyopathy, lethal arrhythmias, or predeliction to a rapidly fatal myocarditis." (PMID 31705601, 2020).
COVID-19 (3 papers, 2021 to 2023). A disease caused by infection with severe acute respiratory syndrome coronavirus 2. "Based on our findings, PPA2 can increase the risk of COVID-19, so PPA2 may be a potential factor that results in SCD in COVID-19 patients." (PMID 34290742, 2021). "Through functional analysis, we found that UQCRH participates in cardiac muscle contraction, PPA2 is closely related to SCD, and myocardial damage and SCD occurred in patients with COVID-19." (PMID 34290742, 2021).
Arrhythmia (2 papers, 2020 to 2023). Any cardiac rhythm other than the normal sinus rhythm. "Mutations leading to a severe reduction of PPA2 activity results in early onset mitochondriopathy with lactic acidosis, seizures, muscular hypotonia and cardiac arrhythmia leading to an early death, commonly within the first 2 years of life." (PMID 37269378, 2023). "Biallelic PPA2 variants display seizures, mildly delayed motor milestones, and cardiac arrhythmia." (PMID 33426505, 2020). "Our patients and others with a higher residual PPA2 activity present in youth or young adulthood with an isolated cardiac expression, myocardial fibrosis, ventricular dilatation, and arrhythmias." (PMID 37269378, 2023).
cardiac failure (2 papers, 2021 to 2024). "We report 34 individuals from 20 previously unreported families with at least one member affected by rapidly progressive cardiac failure or sudden unexplained death and harboring biallelic PPA2 variants." (PMID 34400813, 2021). "The NDUFA6 p.Ile94LysfsTer44 variant has been reported in a patient with recurrent exertional rhabdomyolysis, and the C1QBP p.Thr40AsnfsTer45 and PPA2 p.Glu172Lys variants have been reported in autosomal recessive mitochondrial cardiomyopathies with heart failure and sudden cardiac death." (PMID 39457051, 2024).
colon adenocarcinoma (2 papers, 2021 to 2025). "Interestingly, PPA2 also displayed prognostic value in several other cancers, including breast invasive carcinoma, colon adenocarcinoma, kidney renal papillary cell carcinoma, brain lower grade glioma, and uveal melanoma." (PMID 34567842, 2021). "RNA-seq data for rectum adenocarcinoma (READ) and colon adenocarcinoma (COAD) from the TCGA database also confirmed that reduced PPA2 expression was correlated with advanced tumor stages (Fig. EV1C,D)." (PMID 40164945, 2025).
prostate carcinoma (2 papers, 2011 to 2024). A carcinoma that arises from epithelial cells of the prostate gland. "Protein network analysis and clustering of differentially expressed proteins revealed new targets such as DDAH1, ARG2, EIF4A3, Par4, PPA2, Prdx3 and Prdx4, which need further validation to define their potential application in clinical relevance in prostate cancer." (PMID 21347291, 2011).
Alzheimer disease (1 paper, 2025). A progressive, neurodegenerative disease characterized by loss of function and death of nerve cells in several areas of the brain leading to loss of cognitive function such as memory and language. "Calculation deficits have been reported in pwPPA and Alzheimer’s disease, especially when there is involvement of the inferior parietal lobe, as is the case for participants PPA2 and PPA4, and suspected in PPA1 and PPA3 based on clinical and biomarker findings." (PMID 41300200, 2025).
breast carcinoma (1 paper, 2024). "We also have demonstrated that PPA2 promoted the process of breast cancer." (PMID 39176095, 2024). "At last, we confirmed that PPA2 promotes the progression of breast cancer cells." (PMID 39176095, 2024). "Hence, the aim was to analyze the potential functions of PPA2 in pan-cancer, focusing on its role in breast cancer." (PMID 39176095, 2024). "Finally, we also conducted functional experiments in breast cancer cell lines, and found that PPA2 knockdown inhibited the proliferation, migration and invasion of tumor cells, which also suggested that PPA2 might promote the progression of breast tumor." (PMID 39176095, 2024).
breast tumor (1 paper, 2024). "In conclusion, the results demonstrated the great value of PPA2 in pan-cancer research, as well as its potential as a therapeutic target for breast tumors." (PMID 39176095, 2024).
cognitive deficits (1 paper, 2025). "Our participants’ histories (e.g., PPA2’s four-year diagnostic delay and severity, the presence of general cognitive deficits...) exemplify the impact of current gaps in the assessment of Catalan-speaking individuals." (PMID 41300200, 2025).
colorectal cancer (1 paper, 2025). A primary or metastatic malignant neoplasm that affects the colon or rectum. "Our findings reveal a tumor-suppressive role of PPA2 in HIF-1alpha-dependent colorectal cancer, providing a potential therapeutic target and prognostic strategy." (PMID 40164945, 2025). "This study identifies inorganic pyrophosphatase 2 (PPA2) as a suppressor of metastasis in colorectal cancer, controlling hypoxia-inducible factor-1alpha (HIF-1alpha) stability and glycolytic gene expression." (PMID 40164945, 2025).
External ophthalmoplegia (1 paper, 2021). Paralysis of the external ocular muscles. "The remaining case presenting neurological signs is individual II-1 in family 17, with biallelic p.(Leu278Ser) and p.(Glu172Lys) PPA2 variants, who developed peripheral neuropathy, external ophthalmoplegia, and ptosis from 29 years of age." (PMID 34400813, 2021).
kidney cancer (1 paper, 2021). Primary or metastatic malignant neoplasm involving the kidney. "This analysis showed that PPA2 was expressed at lower levels not only in KIRC, but also in two other common kidney cancer types." (PMID 34567842, 2021).
retinoblastoma (1 paper, 2024). A malignant tumor that originates in the nuclear layer of the retina. "For instance, such as retinoblastoma (RB), PPA2 is positively correlated with anti-angiogenesis, inflammation, and differentiation; it is negatively correlated with DNA repair, cell cycle, and DNA damage." (PMID 39176095, 2024).
viral infections (1 paper, 2021). "Biallelic hypomorphic variants in PPA2, encoding the mitochondrial inorganic pyrophosphatase 2 protein, have been recently identified in individuals presenting with sudden cardiac death, occasionally triggered by alcohol intake or a viral infection." (PMID 34400813, 2021). "We propose that viral infections in affected individuals may tip the cardiac muscle into ATP deficit, due to a build-up of PPi following the effects of temperature increase on the already deficient PPA2 enzyme of these individuals." (PMID 34400813, 2021).
tumor (10 papers, 2018 to 2025). "Compared to rPPA2 WT, rPPA2 K176E significantly abrogated PPA2-deficiency-induced tumor cell migration and invasion under hypoxic stress." (PMID 40164945, 2025). "Consistently, under long-term hypoxic conditions, decreased cell viability in rPPA2 K176E rescued group compared to that of rPPA2 WT also demonstrated that rPPA2 K176E effectively counteracted PPA2-deficiency induced hypoxia resistance of tumor cells." (PMID 40164945, 2025). "Collectively, our findings suggest that PPA2 deficiency facilitates tumor cell migration and invasion in vitro, and decreased PPA2 is associated with mCRC, leading to a poor prognosis at advanced stages of CRC." (PMID 40164945, 2025). "We first analyzed the association between PPA2 expression levels and Tumor Mutation Burden (TMB)." (PMID 39176095, 2024). "To validate our bioinformatics findings, we performed qRT-PCR, immunoblotting (IB), and immunohistochemistry (IHC) analyses to examine PPA2 expression in paired CRC tumor and adjacent peritumoral tissues, and showed lower PPA2 expression in CRC tissues." (PMID 40164945, 2025). "To validate the impact of PPA2 on tumor metastasis in vivo, we established a mouse xenograft model of liver metastasis by splenic injection of PPA2-depleted or PPA2-overexpressed DLD1 cells into BALB/c-nude mice." (PMID 40164945, 2025). "Transwell migration and invasion assays under normoxia and hypoxic conditions demonstrated that PPA2 depletion significantly enhanced the migration and invasion of tumor cells under hypoxic stress." (PMID 40164945, 2025). "It was found that these immune-related pathways were strongly correlated with PPA2 expression levels in most tumor types." (PMID 39176095, 2024). "PPA2, a serine/threonine phosphatase, acts as an inducer of apoptosis and as a human tumor suppressor and has been described to decrease CAT activity." (PMID 36555526, 2022). "The CNVs in C1 were mainly associated with tumor cell proliferation, such as the amplification of 5q31.3 (KCTD16) and 7p22.2 (SDK1), as well as the deletion of 4q24 (PPA2)." (PMID 34804944, 2021). "In this study, by performing IHC in samples from 150 KIRC patients, we found that PPA2 expression was significantly lower in tumor tissues compared than in normal renal tissues, and that lower PPA2 expression was significantly correlated with patient OS." (PMID 34567842, 2021). "Immunohistochemical staining on the tissue microarray showed that PPA2 was primarily expressed in the cytoplasm of KIRC cells, and that the protein expression level of PPA2 in tumor tissues was significantly lower than that in normal renal tissues." (PMID 34567842, 2021). "Consequently, the expression of HIF-1α target genes is inhibited by PPA2, which subsequently inhibits tumor cells’ glycolytic, survival and metastatic capabilities." (PMID 40164945, 2025). "Similarly, reduced PPA2 level was also observed in primary tumor tissues from CRC patients with metastasis compared to those without." (PMID 40164945, 2025). "Hence, we sought to determine the relationship between the function of PPA2 and hypoxic stress in tumor metastasis." (PMID 40164945, 2025). "These indicators are considered to be predictors of tumor immunotherapy response, so the analysis of the correlation between the expression level of PPA2 and these indicators is also to observe the immune value of PPA2 in the treatment of different tumors." (PMID 39176095, 2024). "In addition, the mutant-allele tumor heterogeneity (MATH) and the Neoantigen (NEO) analysis results also indicated that PPA2 expression levels were associated with them in many tumors." (PMID 39176095, 2024). "Which confirmed that knocking down PPA2 expression levels inhibited tumor progression." (PMID 39176095, 2024). "At last, we found that PPA2 expression is mainly distributed in mitochondria in the subcellular structure, and the results of immunofluorescence in different tumor cells also confirmed this conclusion." (PMID 39176095, 2024).
tumor (continued). "Additionally, we identified a novel role for PPA2 in the progression of CRC, in which PPA2 deficiency in combination with hypoxic stress synergistically enhanced glycolysis and migration in vitro and facilitated tumor metastasis in vivo." (PMID 40164945, 2025). "Thus, we focused on studying the function of PPA2 in tumor metastasis." (PMID 40164945, 2025). "It suggested that PPA2 might be expressed highest in tumor cells." (PMID 34567842, 2021). "Clear differences in normal cell and tumor cell responses to LD and HD were observed, which likely depend on AKT activation regulated by protein phosphatase 2 (PPA2)." (PMID 37511215, 2023). "RNA-seq analysis of PPA2-depleted DLD1 cells revealed significant enrichment of the HIF-1 signaling pathway (Fig. EV2A), suggesting a potential link between PPA2 and cellular response to hypoxic stress, a critical factor in tumor metastasis." (PMID 40164945, 2025). "Our study also showed that PPA2 expression was significantly differential between groups with different stromal scores or ESTIMATE scores, suggesting that the tumor microenvironment might affect PPA2 expression." (PMID 34567842, 2021). "Therefore, we propose that inhibiting SIRT5’s desuccination activity on PPA2 could specifically target HIF-1α for ubiquitination and degradation in tumor cells without affecting normal cells." (PMID 40164945, 2025).
cancer (5 papers, 2020 to 2025). A tumor composed of atypical neoplastic, often pleomorphic cells that invade other tissues. "Considering that energy metabolism reprogramming is a hallmark of cancer and that phosphorylation/dephosphorylation is critical in biological processes, we explored the clinical significance and possible role of PPA2, an inorganic pyrophosphatase, in KIRC." (PMID 34567842, 2021). "As a result, our initial discovery revealed that PPA2 expression was aberrant in various types of cancers, showing higher levels in multiple tumors than in normal tissues." (PMID 39176095, 2024). "At the same time, the genomic heterogeneity (including TMB, MSI, MATH, and NEO) of PPA2 in pan-cancer was analyzed." (PMID 39176095, 2024). "Further, we performed survival curves for cancers with statistically different OS levels of high PPA2 expression with a poor prognosis." (PMID 39176095, 2024). "In these cancers, we found that PPA2 expression was significantly correlated with RNA-modifying genes among the majority of tumors." (PMID 39176095, 2024). "In conclusion, we have conducted a series of analyses of PPA2 in pan-carcinoma, including its expression level in tumors and clinical prognostic value, as well as basic biological characteristics, especially its role in immunity." (PMID 39176095, 2024). "Inorganic pyrophosphatase (PPA2) is an enzyme that catalyzes the hydrolysis of pyrophosphate to inorganic phosphate; few studies have reported its significance in cancers." (PMID 34567842, 2021). "To confirm these results, we further explored the prognostic potential of PPA2 in a pan-cancer dataset (including 33 cancer types and 9,486 patients in total) from TCGA using the GEPIA2 platform." (PMID 34567842, 2021). "PPA2 plays an important biological function in many diseases, but whether it plays a corresponding biological function in cancer?" (PMID 39176095, 2024). "Thus, this study aimed to investigate the prognostic value and diverse molecular biological functions of PPA2 in various types of cancer." (PMID 39176095, 2024). "Kaplan-Meier survival analysis for PPA2 in pan-cancer (33 kinds of cancer from TCGA)." (PMID 34567842, 2021). "However, the prognostic value of PPA2 in cancer has rarely been reported." (PMID 34567842, 2021). "However, the specific role of PPA2 in other types of cancer, including CRC, remains unknown." (PMID 40164945, 2025). "However, whether PPA2 has a similar prognostic value to PPA1 in cancer remains unknown." (PMID 34567842, 2021). "Furthermore, other CRRGs, such as PPA2, DGAT1, and CABYR, have been shown to be involved in the oncogenic effects of other cancers and to affect patient prognosis, despite the fact that related studies are uncommon in BC." (PMID 36685904, 2022). "Furthermore, analysis of the TCGA pan-cancer dataset obtained from the UCSC Xena project revealed that PPA2 expression was downregulated exclusively in CRC (including COAD and READ) compared to corresponding normal tissues, but not in other cancer types." (PMID 40164945, 2025).